RINT1 (RAD50 interactor 1)
Description:
Involved in regulation of membrane traffic between the Golgi and the endoplasmic reticulum (ER); the function is proposed to depend on its association in the NRZ complex which is believed to play a role in SNARE assembly at the ER. May play a role in cell cycle checkpoint control. Essential for telomere length control.
Synonyms: RINT-1; FLJ11785; ILFS3
Tractability: Antibody: UniProt places it where antibodies can reach, with medium confidence. PROTAC: ubiquitination databases record sites on it; its protein half-life has been measured.
Gene: Protein-coding gene on chromosome 7 (105,532,160 to 105,567,687, forward strand). Ensembl gene ENSG00000135249.
Subcellular location: Cytoplasm; Endoplasmic reticulum membrane
Subcellular location (Human Protein Atlas): Golgi apparatus
Pathways (Reactome):
Vesicle-mediated transport: COPI-dependent Golgi-to-ER retrograde traffic
Gene Ontology:
Molecular function: protein binding
Biological process: mitotic G2 DNA damage checkpoint signaling; regulation of ER to Golgi vesicle-mediated transport; retrograde vesicle-mediated transport, Golgi to endoplasmic reticulum
Cellular component: Dsl1/NZR complex; endoplasmic reticulum; cytosol; cytoplasm; endoplasmic reticulum membrane
Genetic constraint (gnomAD): Loss-of-function variants: 58 observed, 77.51 expected, observed/expected ratio (o/e) 0.75, 90% interval 0.61 to 0.93. The upper end of that interval is the gene's LOEUF score, 0.93, which puts it in group 3 of 6, group 1 being the genes least tolerant of losing a copy. Missense variants: 751 observed, 823.3 expected, observed/expected ratio (o/e) 0.91, 90% interval 0.86 to 0.97. Synonymous variants: 264 observed, 296.57 expected, observed/expected ratio (o/e) 0.89, 90% interval 0.8 to 0.99.
Gene-disease validity (ClinGen):
ClinGen rates the evidence that RINT1 causes each of these diseases.
hereditary breast carcinoma (autosomal dominant): Refuted. Breast carcinoma that has developed in relatives of patients with history of breast carcinoma.
familial ovarian cancer (autosomal dominant): No Known Disease Relationship. An instance of ovarian cancer that is caused by an inherited modification of the individual's genome.
Homologues: Orthologues: chimpanzee RINT1 (99% identical), macaque RINT1 (99% identical), pig RINT1 (94% identical), dog RINT1 (93% identical), rabbit RINT1 (91% identical), guinea pig RINT1 (90% identical), rat Rint1 (88% identical), mouse Rint1 (88% identical), tropical clawed frog rint1 (73% identical), zebrafish rint1 (58% identical), Drosophila melanogaster Rint1 (26% identical).
Diseases named in the same sentence as RINT1 in open-access papers:
RINT1 is named in the same sentence as 33 diseases in open-access papers, as found by Europe PMC text mining. Sharing a sentence is not in itself a finding about the gene and the disease. The quoted sentences say what the papers report.
breast carcinoma (4 papers, 2017 to 2025). "Whole exome sequencing in families with previously unexplained hereditary breast cancer identified three different germline Rint1 variants, each found in a single family." (PMID 28264000, 2017). "Most recently, germline variants in Rint1 have been associated with increased risk for breast cancer as well as Lynch syndrome type cancers, including colorectal, endometrial, and gastric cancers." (PMID 28264000, 2017). "The RINT1 gene, located on chromosome 7q22.3, has been associated with additional disorders beyond ALF, including early-onset breast cancer, hereditary spastic paraplegia, and cancers within the Lynch syndrome spectrum." (PMID 41158795, 2025). "Although the association of RINT1 gene with breast cancer has been shown, there is no detailed study of its effect." (PMID 32283892, 2020). "Although a small fraction of ApcMin/+ mice spontaneously develop mammary tumors, this phenotype was not enhanced in Rint1+/-; ApcMin/+ mice (data not shown)." (PMID 28264000, 2017).
Lynch syndrome (4 papers, 2017 to 2025). An autosomal dominant hereditary neoplastic syndrome characterized by the development of colorectal carcinoma and a high risk of developing endometrial carcinoma, gastric carcinoma, ovarian carcinoma, renal pelvis carcinoma, and small intestinal carcinoma. "Germline variants in the human RINT1 gene have been associated with increased risk of various cancers associated with Lynch Syndrome, including intestinal cancers." (PMID 28264000, 2017). "It has been previously reported that RINT1 may be associated with Lynch syndrome." (PMID 32283892, 2020). "RINT1 mutations were identified in patients of the ALF multisystem developmental disorder and in patients of Lynch syndrome, that often presents retinal pigment epithelium hypertrophy (CHRPE)." (PMID 32850831, 2020).
liver failure (3 papers, 2021 to 2025). A liver disease characterized by the liver losing or has lost all of its function. "Thus, our results suggest a convergent disease etiology for optic nerve atrophy, muscular hypotonia, neurodevelopmental delay, and liver failure phenotypes observed in RINT1- and NBAS-deficient patients." (PMID 37463447, 2023). "Altered lipid metabolism may also contribute to the liver failure seen in patients with RINT1-associated diseases." (PMID 37463447, 2023). "Other diseases affecting STX18 complex function such as RINT1 deficiency, which is associated with recurrent liver failure and skeletal abnormalities and hence shows phenotypic overlap to NBAS deficiency, should be investigated for trafficking of cytolytic vesicles and impaired NK cell cytotoxicity." (PMID 34386911, 2021).
acute liver failure (2 papers, 2023 to 2025). Rapid deterioration of liver function causing encephalopathy and coagulopathy. "Mutations in the RINT1 gene represent a rare genetic cause of recurrent fever-associated acute liver failure (ALF) accompanied by skeletal abnormalities in infants and children." (PMID 41158795, 2025).
colon cancer (2 papers, 2017 to 2022). "Quantitative PCR analysis of a small number of colon tumors from Rint1+/-; ApcMin/+ mice indicated that the wild type allele of Rint1 was not lost somatically in these tumors (data not shown) and Rint1 expression is not reduced in colon tumors in ApcMin/+ mice." (PMID 28264000, 2017).
colorectal cancer (2 papers, 2017 to 2026). A primary or metastatic malignant neoplasm that affects the colon or rectum. "We also evaluated colorectal cancer data available in the COSMIC and ONCOMINE databases and found that RINT1 overexpression, as well as the presence of somatic missense mutations in RINT1 were associated with colorectal cancer development." (PMID 28264000, 2017). "Rather, analyses of available colorectal cancer data in these databases suggested that overexpression of RINT1 as well as somatic missense mutations in RINT1 may be associated with colorectal carcinogenesis." (PMID 28264000, 2017). "To provide an integrated mechanistic view of our findings, we developed a schematic model summarizing the molecular pathway by which RNF39 regulates colorectal cancer cell proliferation via RINT1‐mediated ER stress responses." (PMID 41457280, 2026). "In summary, our study establishes RNF39 as a critical mediator of colorectal cancer progression through its regulation of RINT1 stability and ER stress responses." (PMID 41457280, 2026). "In this study, we identify RNF39 as a previously uncharacterized RING‐type E3 ubiquitin ligase that drives colorectal cancer progression by promoting ubiquitin–proteasome–mediated degradation of RINT1 and dampening ER stress–induced apoptosis." (PMID 41457280, 2026). "Depletion of RINT1 facilitates ER homeostasis and supports colorectal cancer cell growth by limiting activation of the UPR." (PMID 41457280, 2026). "Therapeutically, targeting RNF39 or disrupting its interaction with RINT1 could sensitize colorectal cancer cells to chemotherapy and ER stress–based treatments." (PMID 41457280, 2026). "Together, these results support the conclusion that RINT1 is a direct substrate of RNF39‐mediated ubiquitination and proteasomal degradation in our colorectal cancer models." (PMID 41457280, 2026). "Altogether, these data are more consistent with the hypothesis that RINT1 functions as an oncogene rather than a tumor suppressor gene in the context of colorectal cancer." (PMID 28264000, 2017).
colorectal tumors (2 papers, 2017 to 2026). "Furthermore, we note that just 0.16% (1 of 607) colorectal tumors in the COSMIC database showed loss of RINT1 expression." (PMID 28264000, 2017).
lymphoma (2 papers, 2017 to 2024). A malignant (clonal) proliferation of B- lymphocytes or T- lymphocytes which involves the lymph nodes, bone marrow and/or extranodal sites. "We note that in the original description of the tumor susceptibility in Rint1+/- mice, the majority of the mice (29%) developed lymphomas." (PMID 28264000, 2017). "It has been reported previously that mice heterozygous for the Rint1 knockout allele spontaneously develop lymphomas as well as solid tumors." (PMID 28264000, 2017). "Approximately 80% of mice heterozygous for the Rint1 knockout allele (Rint1tm1Whl/+) were reported to develop spontaneous lymphomas or solid tumors affecting a variety of tissues including the liver, lung, and uterus." (PMID 28264000, 2017). "Indeed, RINT-1 haploinsufficiency in Rint-1+/− mice promotes chromosomal instability, which in turn stimulates the development of multiple tumours including lymphomas, lung cancers, hepatocellular carcinomas, uterus and breast tumours." (PMID 39839669, 2024).
Acetabular dysplasia (1 paper, 2025). A smaller than normal acetabulum that has insufficient femoral head coverage leading to abnormal hip joint contact pressures, instability and pain. "By contrast, skeletal changes associated with RINT1 mutations predominantly involve vertebral dysplasia, acetabular dysplasia, and irregular femoral head epiphyses, suggesting distinct underlying pathobiological mechanisms." (PMID 41158795, 2025).
glioblastoma (1 paper, 2017). The most malignant astrocytic tumor (WHO grade IV). "Over-expression of Rint1 promoted anchorage-independent growth of glioblastoma cell lines, whereas shRNA knockdown of Rint1 significantly reduced cell viability." (PMID 28264000, 2017). "By contrast, another study identified Rint1 as a potential oncogene in glioblastoma." (PMID 28264000, 2017).
glioma (1 paper, 2017). A benign or malignant brain and spinal cord tumor that arises from glial cells (astrocytes, oligodendrocytes, ependymal cells). "In addition, increased expression of RAD50 interactor 1 (RINT1) and isocitrate dehydrogenase 1 (IDH1) R132H may represent risk factors for low-grade glioma-related seizures." (PMID 29212163, 2017).
intestinal tumor (1 paper, 2017). "Because 129 strains carried alleles that modify the intestinal tumor phenotype in ApcMin/+ mice, we needed to place the Rint1 knockout allele onto a pure B6 background before we could cross Rint1+/- mice with ApcMin/+ mice." (PMID 28264000, 2017). "However, this analysis revealed that heterozygosity for Rint1 did not impact intestinal tumor number or size." (PMID 28264000, 2017).
neuroblastoma (1 paper, 2017). Neuroblastoma (NB) is the most common solid, extracranial childhood tumor. "In addition to syntaxin 18, Rab18 interacts with ZW10 kinetochore protein (ZW10) and RAD50 interactor 1 (RINT1), which, together with neuroblastoma amplified gene (NAG), are members of the NRZ complex." (PMID 28815213, 2017).
optic nerve hypoplasia (1 paper, 2020). "Inactivation of Rint1 specifically in the RPCs induced optic nerve hypoplasia and mildly affected eye growth." (PMID 32850831, 2020).
cancer (7 papers, 2012 to 2026). A tumor composed of atypical neoplastic, often pleomorphic cells that invade other tissues. "Conversely, RINT1 has been shown to be overamplified in some cancers and capable of inducing cellular transformation when inappropriately overexpressed, indicating that Rint1 also has oncogenic properties." (PMID 28031358, 2017). "Cross‐cancer analyses could reveal whether RNF39‐driven degradation of RINT1 or other substrates is a generalizable mechanism co‐opted by tumour cells to bypass ER stress‐induced apoptosis." (PMID 41457280, 2026). "Altogether, our studies with Rint1+/- mice did not support the idea that the Rint1 knockout allele functioned as either a modifier allele of tumorigenesis in ApcMin/+ mice or a cancer predisposing allele on the B6 background." (PMID 28264000, 2017).
tumor (6 papers, 2014 to 2026). "Crucially, the anti‐tumour phenotypes of RNF39 loss were partially reversed by simultaneous RINT1 knockdown." (PMID 41457280, 2026). "RINT1 has been implicated as a context‐dependent tumour suppressor, yet somatic mutations and dysregulated expression have been associated with colorectal tumorigenesis." (PMID 41457280, 2026). "We observed that the risk of spontaneous tumor development in Rint1+/- mice declined progressively during the process of backcrossing to the B6 strain." (PMID 28264000, 2017). "The tumor predisposition of Rint1 heterozygous mice indicated a role as tumor suppressor." (PMID 32850831, 2020). "However, this tumor susceptibility was lost as we backcrossed the Rint1 knockout onto the B6 background." (PMID 28264000, 2017). "We show that RNF39 is transcriptionally activated by MEF2D and enhances tumour cell proliferation and invasion by suppressing RINT1 accumulation, thereby attenuating UPR activation and preventing ER stress‐induced apoptosis." (PMID 41457280, 2026). "The function of RINT-1 in tumour formation remains a topic of debate, as it has been observed to act as both a tumour suppressor and an oncogene." (PMID 39839669, 2024). "The Rint-1 genomic locus is amplified in multiple tumour types, including glioblastomas and is overexpressed and mutated in human colorectal cancers." (PMID 39839669, 2024). "Rint1 has been postulated to function as a tumor suppressor as well as an oncogene, with its role depending perhaps upon the precise cellular and/or experimental context." (PMID 28264000, 2017). "The spectrum of tumor types observed in these mice was consistent with that reported previously in Rint1+/- mice." (PMID 28264000, 2017). "Rint1 expression is necessary during early mouse development, and it has been demonstrated that Rint1 has tumor suppressor activities and is essential for the maintenance of centrosome integrity and chromosomal stability." (PMID 28031358, 2017). "Mean tumor multiplicity in the Rint1+/-; Mom5129/B6;ApcMin/+ mice was 49.6±4, which was essentially identical to the mean of 49.8±7.4 in Rint1+/+; Mom5129/B6;ApcMin/+ mice (p = 0.47)." (PMID 28264000, 2017). "RINT1 heterozygous mice quite often developed multiple tumors due to haploinsufficiency, suggesting that RINT1 serves as a tumor suppressor." (PMID 25364732, 2014). "This analysis identified 13 candidate interacting proteins, among which RINT1 was prioritized for further investigation based on its established role in ER homeostasis and vesicular trafficking, as well as its reported tumour‐suppressive function in other malignancies." (PMID 41457280, 2026). "Because of the possibility that genetic background might impact the tumor phenotype in Rint1+/- mice, we sought to determine if genetic background might also impact the embryonic lethality associated with homozygosity for the Rint1 knockout allele." (PMID 28264000, 2017). "This study suggests that Rint1 may function as a general tumor suppressor gene." (PMID 28264000, 2017). "Likewise, heterozygosity for the Rint1 knockout allele did not impact mean tumor diameter in ApcMin/+ mice." (PMID 28264000, 2017). "RINT1 acts as a functional downstream effector of RNF39, integrating proteostasis regulation with tumour growth and survival signalling." (PMID 41457280, 2026). "Tumour volume measurements over 4 weeks revealed that RNF39 silencing significantly suppressed tumour growth, while co‐silencing of RINT1 with RNF39 restored tumorigenic potential." (PMID 41457280, 2026). "This possibility cannot be excluded because this original description of the tumor phenotype in Rint1+/- mice did not include a parallel analysis of tumorigenesis in Rint1+/+ mice on this same mixed genetic background." (PMID 28264000, 2017). "Altogether, the expression and somatic mutation spectrum data were more consistent with the idea that RINT1 might function as an oncogene in the context of colon carcinogenesis rather than a tumor suppressor gene." (PMID 28264000, 2017).
tumor (continued). "The fourth Rint1+/- mouse died unexpectedly and could not be evaluated for tumor development." (PMID 28264000, 2017).
movement disorder (1 paper, 2023). Neurological conditions resulting in abnormal voluntary or involuntary movement, which may impact the speed, fluency, quality and ease of movement. "Our findings highlight the crucial role of RINT1 — and, more broadly, the NRZ complex — in neutral lipid and phospholipid metabolism and add a strong piece of evidence pointing at abnormal lipid homeostasis as a culprit in neurodevelopmental and movement disorders." (PMID 37463447, 2023).
RINT1 also shares sentences with these, for which no sentence is quoted: hereditary spastic paraplegia (2 papers); infantile liver failure syndrome 3 (2); Ataxia (1); breast tumours (1); colon adenocarcinoma (1); complex HSP (1); developmental delay (1); hepatocellular carcinoma (1); intestinal cancer (1); lung carcinoma (1); Onset (1); optic atrophy (1); osteogenesis imperfecta (1); Pelger-Huet anomaly (1); SOPH syndrome (1); Spastic paraplegia (1).